TGFB1 (transforming growth factor beta 1)
Diseases named in the same sentence as TGFB1 in open-access papers (continued):
Sharing a sentence is not in itself a finding about the gene and the disease.
pancreatitis (26 papers, 2007 to 2026). Inflammation of the pancreas. "Given the increase in serum TGFβ1 levels and the increased pancreatitis-associated fibrosis in PEDF null mice, we further evaluated the role of PEDF in regulating fibrosis." (PMID 27058416, 2016). "In order to further explore the relationship between the results of this experiment and human AP, we analyzed the expression of three key genes TNF, NOS3, and TGFB1 in human pancreatitis tissues." (PMID 34925503, 2021). "TGFβ1, a key PSC activating factor, is highly expressed and associated with fibrotic mechanisms of pancreatitis, as well as PDAC stromal reaction." (PMID 34464354, 2021). "(G) qRT-PCR for Egf, Tgfα, Hbegf, Tgfβ1 and Tnfα expression in myeloid cells sorted from control spleen, iKras* pancreata 3 weeks post pancreatitis and 3 days post Kras* inactivation." (PMID 28980940, 2017). "In mice, genetic ablation of PEDF leads to enhanced cerulein-induced pancreatitis and poorer recovery, with enhanced early fibrotic effects mediated by TGFβ1." (PMID 27058416, 2016). "One of the most potent fibrogenic modulators is TGFβ1, which is overexpressed in pancreatic acinar and stromal cells after caerulein-induced pancreatitis." (PMID 22133269, 2011). "TGFβ1 upregulation also has been well-documented in human pancreatitis." (PMID 38247878, 2024). "Significantly reduced damage was further substantiated by lower collagen content, alpha smooth muscle actin staining (ACTA2), and transforming growth factor β (Tgfb1) expression in Dkk3‐null animals 96 h after pancreatitis induction, indicating less fibrosis at this time point." (PMID 34306986, 2021). "Therefore, miR-30a-5p silencing induced by its antagomir abrogated the anti-inflammatory activity of emodin in pancreatitis rats, which showed that miR-30a-5p exerted critical regulation in anti-inflammatory effect of emodin by regulating HTRA1/TGFβ1 signaling pathway." (PMID 29163548, 2017). "Therefore, we surmise that the TNF and TGFB1 genes are upregulated by TMAO and that the TGFB gene participates in regulating the expression and activation of TNF, which increases the expression of the inflammatory factor TNF-α and induces a sensitive state of pancreatitis." (PMID 34925503, 2021).
Arrhythmia (25 papers, 2017 to 2026). Any cardiac rhythm other than the normal sinus rhythm. "We aimed to investigate whether early post-PVI levels of C-reactive protein (CRP), white blood cells, tumour necrosis factor alpha (TNF-α) and transforming growth factor beta 1 (TGF-ß1) are associated with long-term arrhythmia recurrence." (PMID 40507635, 2025). "Transforming growth factor beta-1 (TGF-β1), an effective stimulator of fibroblasts, has a pathogenic effect on valvular heart disease and arrhythmias." (PMID 35814223, 2022). "The synergistic effect of TGFβ1 and CTGF induces and aggravates atrial fibrosis, causing AAR and provides the mechanisms underlying arrhythmias, which are closely related to AF." (PMID 30697920, 2019). "The role of transforming growth factor beta 1 (TGF-ß1) in predicting arrhythmia recurrence remains unclear and the results of studies are conflicting." (PMID 40507635, 2025). "The cardiac content of the fibrogenic cytokine TGFβ1 was significantly increased in streptozotocin-induced diabetic rats (p<0.05) compared to control rats, suggesting a correlation between the diabetic cardiac arrhythmias and fibrosis signalling activation." (PMID 29206854, 2017).
autism (25 papers, 2011 to 2025). Persistent deficits in social interaction and communication and interaction as well as a markedly restricted repertoire of activity and interest as well as repetitive patterns of behavior. "Growth factors serve important roles in neurodevelopment, immune function and development of the central nervous system and there is evidence that autism is associated with TGFβ1 and other growth factor-encoding genes." (PMID 40494901, 2025). "Regarding TGFB genes, an increase in protein levels of TGFB1 was reported in postmortem brains and CSF of patients with autism." (PMID 38994948, 2024). "Nevertheless, a human study reported DNA hypomethylation of TGFB1 in the blood cells of patients with autism." (PMID 38994948, 2024). "Where almost half of all TGFB1 promoter DNA methylation in neurons was due to 5-hmC, and the level of 5-hmC in autism was twice as much compared to the control subjects, this difference was not statistically significant." (PMID 38994948, 2024). "The TGFB1 promoter region was almost totally unmethylated in iPSC-derived astrocytes in both the control and autism groups." (PMID 38994948, 2024). "The production of regulatory cytokine-transforming growth factor beta-1 (TGFβ1) was lower in the autism group with GI symptoms." (PMID 36632246, 2022). "Thus, it is likely that the increased expression of TGFB1 in the astrocytes of patients with autism is mediated by DNA hypomethylation of other CpG sites or/and due to different epigenetic mechanisms." (PMID 38994948, 2024). "In postmortem brain tissues of five cases with autism and five control subjects, the TGFB1 promoter region was extensively unmethylated (~5–10% methylation) and there was no significant change between cases and controls, but methylation in autism was 22% less than controls." (PMID 38994948, 2024). "Moreover, the astrocytes of patients with autism exhibited higher expression of TGFB1 and TGFB2 but reduced expression of proliferator genes such as CXCR4 and NURR1 in addition to RELN, EN2, HAP1, SIRT1, and GPX1 vs. controls." (PMID 38994948, 2024). "To determine whether altered expression of TGFB genes occurred before or after differentiation, we analyzed TGFB1, B2 and TGFB3 gene expression in the NSCs of patients with autism and control subjects." (PMID 38994948, 2024).
B-cell lymphoma (25 papers, 2010 to 2026). "In this case, TGFβ1 activation in the B-cell lymphoma resulted in decreased E2F1 expression, leading to reduced ARF transcription." (PMID 32759846, 2020). "Unlike TGFβ2, TGFβ1 participates in a signaling pathway that negatively regulates ARF transcription in B-cell lymphoma." (PMID 32759846, 2020).
fibrosarcoma (25 papers, 2009 to 2025). A malignant mesenchymal fibroblastic neoplasm affecting the soft tissue and bone. "TGFβ1-induced nuclear shape aberrations were also observed in RD (human rhabdomyosarcoma), NMuMG (mouse mammary gland epithelial cell), and HT-1080 (human fibrosarcoma) cells." (PMID 34983624, 2022). "In an early report RHAMM/hyaluronan signaling was found to be obligatory for the stimulation of fibrosarcoma cell migration which is induced by transforming growth factor-beta 1 (TGFβ1)." (PMID 24083250, 2013). "Indeed, signaling is perpetrated through the formation of the RHAMM-HA complex because antibodies that inhibit RHAMM-HA binding simultaneously suppress TGFβ1-induced increases in fibrosarcoma cell motility rate." (PMID 24083250, 2013). "The present study explored the in vivo immunomodulatory effect on interferon-gamma (IFN-γ), interleukin-17 (IL-17), and transforming growth factor-beta 1 (TGF-β1) evoked by two water-extracts prepared from EJ leaves in the tissues of normal and Meth-A-fibrosarcoma bearing mice." (PMID 21294856, 2011).
Hypercholesterolemia (25 papers, 2008 to 2025). An increased concentration of cholesterol in the blood. "Hypercholesterolemia can induce T cell expansion, which plays a key role in the adaptive immune response in humanized immunized mice, and upregulates the expression of transforming growth factor beta 1 (TGFb1) in the liver." (PMID 33546519, 2021).
intervertebral disc degeneration (25 papers, 2013 to 2025). "The accelerated chondrogenesis of hMSCs can be achieved by co-transfection of Sox9 and TGFβ1 resulting in the cure of the manifestations associated with intervertebral disc degeneration." (PMID 37007782, 2023).
myocardial ischemia (25 papers, 2010 to 2026). A disorder of cardiac function caused by insufficient blood flow to the muscle tissue of the heart. "The potential of OSM to counteract the pro-fibrotic effects of TGFβ-1 in cardiac ischemia models has been reported previously." (PMID 37047440, 2023). "Experimentally induced cardiac ischemia through ligation and reperfusion of the left anterior descending coronary artery results in a significant up-regulation of Tgfb1–3 mRNA in the reperfused infarct area in mice and pigs." (PMID 34572573, 2021).
vitamin D deficiency (25 papers, 2013 to 2025). A nutritional condition produced by a deficiency of VITAMIN D in the diet, insufficient production of vitamin D in the skin, inadequate absorption of vitamin D from the diet, or abnormal conversion of vitamin D to its bioactive metabolites. "The association of vitamin D deficiency and TGFβ1/IL-11/p-MEK/p-ERK-dependent fibrosis was also observed in a genetic mouse model of vitamin D deficiency mimicking some effects of FGF-23 overproduction." (PMID 38732588, 2024). "Moreover, in an animal study, vitamin D deficiency increased over the three-fold burden of liver tumor growth in the context of TGF-β (Transforming growth factor beta 1)." (PMID 31350967, 2019). "In a set of experiments examining the effect of maternal vitamin D deficiency on fetal brain development, Hawes and colleagues found that the pups from deficient mothers display a modulated expression of Bdnf, Foxp2, Tgfb1 and Th, which are also affected in certain conditions of our study." (PMID 26932723, 2016).
cholestasis (24 papers, 2009 to 2025). Impairment of the bile flow caused by obstruction within the liver, or outside the liver in the bile duct system. "These new findings suggest that Msln-Muc16-Thy-1 signaling plays an important role in the regulation of TGFβ1-TGFβRI signaling in cholestasis-activated aPFs." (PMID 34966784, 2021).
colon adenocarcinoma (24 papers, 2003 to 2026). "The genes positively correlating with SPARC in breast and colon adenocarcinoma tumors included TGFB1, a powerful stimulator of migration of peritumoral CAFs." (PMID 36604669, 2023). "BRAFV600E induced transforming properties are further enhanced through cooperation with TGFβ-1, suggesting that synergism between oncogene and growth factor is essential for induction of further migration properties in colon adenocarcinoma cells." (PMID 21943101, 2011).
dementia (24 papers, 2012 to 2025). Loss of intellectual abilities interfering with an individual's social and occupational functions. "Transgenic mice overexpressing TGFβ1 in the brain (TGF mice) recapitulate VCID-associated cerebrovascular pathology and develop cognitive deficits in old age or when submitted to comorbid cardiovascular risk factors for dementia." (PMID 38132326, 2023). "IL1B, TNFA, and TGFB1 mRNA levels were significantly higher in sPDD versus the other groups, confirming that also in our cohort, disrupted cytokine signaling correlates with the progression of PD to dementia." (PMID 34234281, 2021).
invasive breast carcinoma (24 papers, 1994 to 2025). A carcinoma that infiltrates the breast parenchyma. "For example, BCAC reported that common coding variants CASP8 D302H in the gene encoding Caspase 8, and TGFB1 L10P in the gene encoding transforming growth factor-β (TGFβ), in one allele (heterozygote) were associated with significant risk to invasive breast cancer." (PMID 21655367, 2008).
chronic lung disease (23 papers, 2007 to 2024). According to the definitions of the American and British Thoracic Societies, including pulmonary functional tests, X-rays, and CT scans for items such as fibrosis, bronchiectasis, bullae, emphysema, nodular or lymphomatous abnormalities. "Here, we update the current perspective on the circadian clock role in TGFβ1 signaling and extracellular matrix production during chronic lung diseases." (PMID 36767821, 2023). "One key growth factor released by these activated fibroblasts is transforming growth factor-β1 (TGFβ1), which plays a major role in ECM remodeling and the subsequent pathogenesis of chronic lung diseases." (PMID 36767821, 2023).
focal segmental glomerulosclerosis (23 papers, 2013 to 2025). A renal disorder characterized by sclerotic lesions in the glomeruli. "These rats exhibited progressive focal interstitial fibrosis, characterized by increased numbers of myofibroblasts, apparently enhanced TGFβ1 expression, and interstitial collagen deposition, as well as evidence of focal glomerulosclerosis." (PMID 28002484, 2016).
infarction (23 papers, 2015 to 2026). A localised pathological necrosis of tissue resulting from obstruction of the blood supply usually by a thrombus, an embolus, or vascular torsion. "As we showed before, TGFβ3 increased gradually with the infarction time, when the ratio of TGFβ1 to TGFβ3 changed, the inhibition of TGFβ3 predominated and the whole body experienced the inhibition effect." (PMID 30983140, 2019). "As determined by Western blot and ELISA, relatively high expression of TGFβ1 and TGFβ2 was detected in the early phase of MI, while TGFβ1 and TGFβ2 expressions decreased with the infarction time." (PMID 30983140, 2019).
prion disease (23 papers, 2009 to 2025). A transmissible disease that is caused by a protein that is able to induce abnormal folding of normal cellular proteins, leading to characteristic spongiform brain changes, which are associated with neuronal loss without an inflammatory response. "The inflammatory phenotype typically associated with prion disease has been shown to be remarkably anti-inflammatory and dominated by the anti-inflammatory growth factor Tgfb1 following injection by an intracerebral or a hippocampal stereotactic route." (PMID 26719249, 2015). "We also noted that 5 of these homeostatic genes typically decreased in MGnD microglia (Csf1r, Fcrls, Hexb, Jun and Tgfb1) were increased in prion disease over time, with two (Fcrls and Jun) upregulated at 100 dpi." (PMID 32381108, 2020). "TGFβ1 promotes neurogenesis by promoting quiescent microglia in mouse models of prion disease." (PMID 37250395, 2023). "Deficiency of Tgfb1 signaling increases both Aβ accumulation and Aβ-induced neurodegeneration in AD models, and absence of Il10 accelerates prion disease, suggesting neuroprotective roles of Il10-Il10rb signaling." (PMID 31959236, 2020). "TGFB1 is a cytokine which is overexpressed in prion disease." (PMID 23068602, 2012). "All these mediators are produced by intracerebral LPS challenges, but TGFβ1 and PGE2 would appear to dominate in ME7-induced prion disease." (PMID 19459212, 2009).
Anxiety (22 papers, 2014 to 2025). Intense feelings of nervousness, tension, or panic often arise in response to interpersonal stresses. "SAMe’s effects to increase TGFβ1, improve branching and decrease the quantity of microglia in the dorsal hippocampus may have aided in reducing some anxiety-like behaviors in obese mice." (PMID 33917279, 2021). "Furthermore, mice lacking hippocampal PHD and ring finger domaine 1 (PHRF1), which is essential for TGFβ1 signaling, displayed increased anxiety-like behavior." (PMID 33917279, 2021). "Therefore, the TGFβ-1 inhibitor does not affect the mobility, weight, or anxiety levels of the rats suggesting that the effect is specific to learning." (PMID 31829243, 2019).
dermatitis (22 papers, 2011 to 2026). An inflammatory process affecting the skin. "In dermatitis research, it was observed that TGFβ1 overexpression in mouse epidermis induced inflammatory skin lesions and Koebner’s phenomenon, indicating the pro-inflammatory role of TGFβ1." (PMID 38360663, 2024).
leprosy (22 papers, 2011 to 2024). Leprosy is a chronic infectious disease affecting primarily the skin and peripheral nervous system. "Applying the strategy proposed by Gaschignard and researchers, we conducted an association study of IL2RA and TGFB1 candidate genes in the “leprosy polarisation” phenotype, as this is a needy focus of inquiry in genetic epidemiology of leprosy." (PMID 30540075, 2018). "OBJECTIVES We conducted an association study for IL2RA and TGFB1 genes with clinical forms of leprosy based on two case-control samples." (PMID 30540075, 2018). "When testing the TGFB1 gene, we found an association between the AA genotype of the polymorphism rs1800470 to the risk of MB leprosy in both populations." (PMID 30540075, 2018). "SNP rs1800470 of the TGFB1 gene is associated with MB leprosy - For the start population, the rs1800470 marker in the TGFB1 gene was tested." (PMID 30540075, 2018). "As a result, our data points to IL2RA and TGFB1 associations with leprosy polarisation and help to construct the genetic architecture of this neglected phenotype." (PMID 30540075, 2018).
osteogenesis imperfecta (22 papers, 2015 to 2026). Osteogenesis imperfecta (OI) comprises a heterogeneous group of genetic disorders characterized by increased bone fragility, low bone mass, and susceptibility to bone fractures with variable severity. "TGFβ1 is a multifunctional protein with key roles in bone and muscle physiology; perturbations in the TGFβ1 signalling pathway are associated with multiple skeletal dysplasias (e.g. osteogenesis imperfecta type IV (OMIM 166220), acromicric dysplasia (OMIM 102370) and Loeys-Dietz syndrome types 1–5." (PMID 40811023, 2025). "There is an opposing relationship between TGFβ1 and PEDF in a study on type VI osteogenesis imperfecta pathogenesis using Serpinf1 (−/−) mouse osteoblasts." (PMID 37108600, 2023).
pterygium (22 papers, 2013 to 2025). A wedge-shaped fibrovascular lesion arising from the bulbar conjunctiva and extending to the cornea. "Given the association of TGFB1 with inflammation and its pro- and anti-inflammatory responses, it likely plays multi-functional roles in pterygium pathology, encompassing inflammation, stress response, and tissue remodeling." (PMID 38732006, 2024). "The role of TGFB1 in tissue remodeling, particularly its interaction with fibroblasts, is implicated in pterygium tissue remodeling." (PMID 38732006, 2024). "The TGF-β1 (Transforming Growth Factor Beta 1) gene showed a significant increase, with its expression being markedly upregulated in recurrent pterygium tissue compared to primary pterygium tissue (p = 0.034)." (PMID 39682531, 2024).
Uterine leiomyoma (22 papers, 2010 to 2026). The presence of a leiomyoma of the uterus. "We observed multiple deregulated signaling pathways, including those for IGF-1, neuregulin, mTOR, TGFB1, CTNNB1, and TNF, in the mouse uterine leiomyomas." (PMID 33244099, 2020).